PCDHB15 (protocadherin beta 15)
Description:
Potential calcium-dependent cell-adhesion protein. May be involved in the establishment and maintenance of specific neuronal connections in the brain.
Synonyms: PCDH-BETA15
Tractability: Antibody: its Gene Ontology location is reachable by antibodies, with high confidence; UniProt places it where antibodies can reach, with medium confidence; UniProt predicts a signal peptide or a membrane-spanning region. PROTAC: ubiquitination databases record sites on it.
Gene: Protein-coding gene on chromosome 5 (141,245,395 to 141,249,365, forward strand). Ensembl gene ENSG00000113248.
Subcellular location: Cell membrane
Subcellular location (Human Protein Atlas): Basal body; Centrosome; Nucleoplasm
Gene Ontology:
Molecular function: cell adhesion molecule binding; calcium ion binding
Biological process: cell adhesion; nervous system development; homophilic cell-cell adhesion
Cellular component: plasma membrane; membrane; photoreceptor connecting cilium
Genetic constraint (gnomAD): Loss-of-function variants: 0 observed, 0.53 expected, observed/expected ratio (o/e) 0, 90% interval 0 to 1.83. That is too few expected variants to judge how well the gene tolerates losing a copy. Missense variants: 1,032 observed, 1,021.7 expected, observed/expected ratio (o/e) 1.01, 90% interval 0.96 to 1.06. Synonymous variants: 492 observed, 457.17 expected, observed/expected ratio (o/e) 1.08, 90% interval 1 to 1.16.
Homologues: Orthologues: chimpanzee PCDHB15 (98% identical), macaque PCDHB15 (95% identical), mouse Pcdhb22 (75% identical), rat Pcdhb22 (75% identical), guinea pig PCDHB15 (74% identical), dog PCDHB15 (72% identical). Paralogues in human: PCDHB3 (78% identical), PCDHB4 (76% identical), PCDHB16 (76% identical), PCDHB6 (76% identical), PCDHB5 (76% identical), PCDHB14 (76% identical), PCDHB8 (75% identical), PCDHB13 (75% identical), PCDHB2 (75% identical), PCDHB7 (75% identical), PCDHB9 (75% identical), PCDHB10 (75% identical), and 49 more.
Diseases named in the same sentence as PCDHB15 in open-access papers:
PCDHB15 is named in the same sentence as 13 diseases in open-access papers, as found by Europe PMC text mining. Sharing a sentence is not in itself a finding about the gene and the disease. The quoted sentences say what the papers report.
breast carcinoma (4 papers, 2015 to 2023). "PCDHB15 is involved in cell adhesion, and it is epigenetically regulated in melanoma and breast cancer cells." (PMID 37873862, 2023). "More recently, PCDHB15 was proposed as a potential tumor suppressor in breast cancer, based on the observation of a positive correlation between PCDHB15 expression and relapse-free survival." (PMID 36443814, 2022). "In addition, in breast cancer, PCDHB15, a potential tumor suppressor, was reported to be epigenetically silenced via DNA promoter methylation, and it might be an epigenetic biomarker for the diagnosis and prognosis of breast cancer." (PMID 35465267, 2022). "Interestingly, a negative correlation between PCDHB15 promoter methylation and PCDHB15 expression was also reported in breast cancer." (PMID 36443814, 2022).
colon cancer (2 papers, 2015 to 2022). "In concordance with our findings, PCDHB15 was identified as a part of a specific methylation signature across breast and colon cancer, as PCDHB13 in Non-Small Cell Lung Cancer." (PMID 36443814, 2022).
melanoma (2 papers, 2022 to 2023). A malignant, usually aggressive tumor composed of atypical, neoplastic melanocytes. "Lower aggregation upon PCDHB15 overexpression is associated with impaired 3D invasiveness, suggesting the potential importance of an aggregative behavior in the invasive abilities of melanoma cells." (PMID 36443814, 2022). "In vivo experiments have shown that PCDHB15 overexpression in melanoma promote cell invasion, cancer cell aggregation, and lung metastasis." (PMID 37873862, 2023). "Taken together, these in vitro effects suggest that silencing of PCDHB15 in melanoma cells participates in the fine-tuning of the aggregative behavior of melanoma cells during melanoma progression and favors specific metastatic properties." (PMID 36443814, 2022). "In this study, we demonstrate an epigenetic regulation of the expression of the PCDHB15 gene in melanoma cell lines." (PMID 36443814, 2022). "Taken together, our data suggest for the first time a potential role of tumor suppressor for PCDHB15 in melanoma." (PMID 36443814, 2022). "For the first time, our findings support a potential role of PCDHB15 silencing contributing to melanoma aggressiveness by important DNA methylation modifications of the gene." (PMID 36443814, 2022). "Next, we studied the effect of the overexpression of PCDHB15 on the aggregation of melanoma cells by monitoring the spontaneous formation of spheroids in the metastatic WM266-4 cell line and the three clones." (PMID 36443814, 2022). "Here, we show that PCDHB15, a member of this cluster of genes, marks melanoma aggressiveness and plays a functional role in regulating the hallmarks of cancerogenesis." (PMID 36443814, 2022). "More recently, by comparing the genomic repartition of DNA methylation in cell lines of different aggressiveness status, we identified clusters of DNA hypermethylation that characterizes melanoma aggressiveness and, in particular, the gene PCDHB15." (PMID 36443814, 2022). "We explored the role of PCDHB15 in melanoma aggressiveness and showed that overexpression impairs invasiveness and aggregation of metastatic melanoma cells in vitro and formation of lung metastasis in vivo." (PMID 36443814, 2022). "Among the aberrant methylated CpGs patterns that mark melanoma aggressiveness in patient primary tumors, we found the PCDHB15 gene." (PMID 36443814, 2022). "We showed that PCDHB15 is strongly DNA hypermethylated at the 5′ end of its single exon, in the most aggressive melanoma cell lines compared to the less aggressive ones, as well as in the metastases compared to the corresponding primary melanomas." (PMID 36443814, 2022). "In addition, overexpression of PCDHB15 impaired metastatic melanoma cell invasiveness and aggregation in vitro, and metastasis formation in vivo." (PMID 36443814, 2022). "Here, we evaluated whether the treatment with the demethylation agent, 5azadC, at low doses reverts PCDHB15 silencing, as we have shown that 5azadC treatment at low doses reverted melanoma cell invasion in 3D invasion assays and in vivo metastasis formation." (PMID 36443814, 2022). "The inhibitory effect of PCDHB15 overexpression on in vitro melanoma cell aggregation and invasion led us to investigate the capacity of PCDHB15 expressing melanoma cells to form lung metastasis in mice after intravenous injection as does the metastatic WM266-4 cell line." (PMID 36443814, 2022).
metastatic melanoma (2 papers, 2022). A melanoma that has spread from its primary site to another anatomic site. "We have identified for the first time that PCDHB15 gene is DNA-hypermethylated on its unique exon in the metastatic melanoma-derived cell lines and patients’ metastases compared to primary tumors." (PMID 36443814, 2022). "We observed that PCDHB15 is hypermethylated at the 5′ end of its unique exon and is not expressed in two metastatic melanoma-derived cell lines, WM266-4 and WM983A." (PMID 36443814, 2022).
cervical cancer (1 paper, 2013). A primary or metastatic malignant neoplasm involving the cervix. "Among the 49 PRC2 targets (defined by consistent hyper-MVPs) identified here were 10 genes of the cadherin superfamily in HPV+ HNSCC, including CDH8 and CDH13 (both also hypermethylated in cervical cancer, CDH18, CDH19, CDH23, PCDH10, PCDH15, PCDHB1, PCDHB4, and PCDHB15." (PMID 23419152, 2013).
colorectal cancer (1 paper, 2022). A primary or metastatic malignant neoplasm that affects the colon or rectum. "A functional role for the hypermethylation and gene silencing of PCDHαβγ family genes (PCDHAC2, PCDHB7, PCDHB15, PCDHGA1 and PCDHGA6) was also identified recently in colorectal cancer influencing the WNT/B-catenin pathway implicated in proliferation, survival and migration." (PMID 36443814, 2022).
cutaneous melanoma (1 paper, 2022). A primary melanoma arising from atypical melanocytes in the skin. "Considering that neurons and melanocytes are derived from the same embryonic tissue, these findings prompted us to characterize the functional role of PCDHB15 in cutaneous melanoma cells." (PMID 36443814, 2022).
neuroblastoma (1 paper, 2022). Neuroblastoma (NB) is the most common solid, extracranial childhood tumor. "On chromosome 5, two genes were chosen from the PCDHB hypermethylation cluster: PCDHB15 and PCDHB16 that are CIMP-associated with bad prognosis in neuroblastoma." (PMID 36125262, 2022).
ovarian carcinoma (1 paper, 2023). A malignant neoplasm originating from the surface ovarian epithelium. "PCDHB15, another protocadherin identified by us, is expressed in all ovarian cancer patient samples." (PMID 37873862, 2023). "Of paramount significance, we identify three promising ovarian cancer targets suitable for ADC development: LRP6, PCDHB10, and PCDHB15." (PMID 37873862, 2023).
tumor (6 papers, 2009 to 2023). "TCGA data confirm that PCDHB15 hypermethylation is observed in patient metastasis samples compared to primary tumor samples." (PMID 36443814, 2022). "In WM115 and WM266-4 cells which are derived, respectively, from the primary tumor and the cutaneous metastasis of the same patient, PCDHB15 showed differential methylation above 40% in at least two CpGs positions located at + 566 and + 610 pb from the TSS, respectively." (PMID 36443814, 2022). "PCDHB8 and PCDHB15 exhibited strong methylation associated silencing but PCDHB12 was not consistently down-regulated in tumours, despite hypermethylation." (PMID 19956686, 2009). "Four genes (MYH1, PCDHB16, PCDHB15, and BCL2L10) showed a differential methylation profile between metastatic and primary tumour tissue samples (data not shown)." (PMID 36125262, 2022).
cancer (3 papers, 2015 to 2023). A tumor composed of atypical neoplastic, often pleomorphic cells that invade other tissues. "Nonetheless, like other cell adhesion proteins altered in specific cancer types, PCDHB15 can promote cancer cell proliferation and migration." (PMID 37873862, 2023).
PCDHB15 also shares sentences with these, for which no sentence is quoted: non-small cell lung carcinoma (1 paper); retinal degeneration (1).